CD40 (CD40 molecule)
Diseases named in the same sentence as CD40 in open-access papers (continued):
Sharing a sentence is not in itself a finding about the gene and the disease.
colitis (continued). "ILC3s have been identified as the only mediator for disease induction in the anti-CD40-induced colitis model." (PMID 32670290, 2020). "To further demonstrate the importance of CD40 in MC-LR’s mechanism of toxicity in the setting of pre-existing colitis, we utilized a CD40 receptor blocking peptide within WT mice in a proof-of-concept study." (PMID 32498446, 2020). "qPCR analysis also confirmed the effectiveness of CD40 peptide treatment in mice with pre-existing colitis and MC-LR exposure." (PMID 32498446, 2020). "Using a CD40-mediated colitis model, we further validated our CRISPR/Cas9-based platform for investigating gene function in experimental IBD." (PMID 32155151, 2020). "In the current study, we observed that knocking out CD40 ameliorates the effects of MC-LR within the intestines of mice with DSS-induced colitis and also show that treatment with a CD40 blocking peptide mirrors the effects seen with knocking out CD40." (PMID 32498446, 2020). "We also observed that, while the pro-inflammatory and pro-fibrotic cytokines IL-1β, MCP-1, and PAI-1 were upregulated in the WT DSS + MC-LR group, knocking out CD40 prevented their upregulation upon MC-LR exposure in the setting of DSS-induced colitis." (PMID 32498446, 2020). "Similar to IL-10, IL-22 exerts a protective effect on mucosal inflammation in most animal models, but plays a harmful role in the anti-CD40-induced colitis model, which will be discussed later in this section." (PMID 32670290, 2020). "To further understand the interplay between macrophage associated inflammation and permeability, we evaluated the impact of anti-p40 treatment in anti-CD40 colitis animals." (PMID 32170183, 2020). "Our previous study found that MC-LR further enhances the upregulation of CD40 in the setting of pre-existing colitis, along with upregulation of downstream products of CD40 activation, PAI-1 and MCP-1." (PMID 32498446, 2020). "In mice, the IFN-γ-producing ex-ILC3s deteriorate innate colitis induced by anti-CD40 antibody injection when they are transferred to RAG2-/-Il2rgc-/- mice." (PMID 32403291, 2020). "A pathogenic role of ILC3 in colitis has also been suggested by others in mouse models with H. hepaticus and anti-CD40 antibody driven colitis and even IBD patients." (PMID 33603753, 2020). "IL-23 was identified as the main driver of intestinal inflammation in mouse models of T cell transfer colitis, anti-CD40 antibody-driven colitis, Clostridium difficile infection, Helicobacter hepaticus-induced colitis, and Salmonella enterica." (PMID 33488580, 2020). "We therefore concluded that levels of IL-23 in F1DC-LMP1/CD40 mice were insufficient to induce colitis in F1 mice." (PMID 30653608, 2019). "This suggests that blocking of the T cell survival signal IL-1β protects B6DC-LMP1/CD40 mice from colitis and identifies IL-1β as colitis-driver, which is present in B6-, but not F1- nor B/c-background." (PMID 30653608, 2019). "The incidence and severity of disease increased from protected B/c-mice to F1, which showed mild signs of inflammation, and culminated as fatal colitis in DC-LMP1/CD40-mice of the B6 background." (PMID 30653608, 2019). "Colitis in B6DC-LMP1/CD40 mice was accompanied by increased frequencies of LP-infiltrating IL-17+IFN-γ+ CD4+ T cells and IFN-γ+ Th1 cells, corroborating data published previously." (PMID 30653608, 2019). "In contrast, AMD3100 blocked the therapeutic function of ERCs, and much more cells of CD11c+MHCII+, CD11c+CD86+, and CD11c+CD40+ DCs were found in colitis mice treated with AMD3100-pretreated ERCs, which were indistinguishable from that of the untreated group." (PMID 31286993, 2019). "We found that the DR3-Fc-treated mice lost less body weight and recovered sooner than vehicle or IgG-treated group in α-CD40-induced colitis." (PMID 31358760, 2019). "Although their function is not completely understood, NKp46+NK1.1+ IEL have been shown to promote disease development in the anti-CD40 model of colitis." (PMID 31291255, 2019).
colitis (continued). "Future studies will help to further elucidate the role of CD40 in DSS-induced colitis, its role in disease exacerbation in the presence of MC-LR exposure, and its potential as a therapeutic target for disease prevention and reversal." (PMID 31242640, 2019). "We have recently published a novel mouse model, where the DC–iTreg axis was manipulated and mice spontaneously developed colitis due constitutive CD40 signaling in CD11c+ DCs." (PMID 30653608, 2019). "After nine further backcrosses of the B/cGt(ROSA)26Sortm1Uzs to the B6-background (for short: B6DC-LMP1/CD40), we observed fatal colitis in all mice as published previously." (PMID 30653608, 2019). "To find out if IL-1 was responsible for colitis development in B6DC-LMP1/CD40-mice, we next blocked IL-1β by injection of a specific blocking antibody." (PMID 30653608, 2019). "In the CD40-Ab-induced colitis model, mobilization of ILC3s from CPs into adjacent tissue and recruitment of inflammatory monocytes result in the formation of characteristic inflammatory foci." (PMID 29343433, 2018). "This suggests that ILC3 intrinsic IFNγ-production was sufficient for induction of acute intestinal inflammation in the anti-CD40 innate colitis model." (PMID 29416538, 2018). "Taken together, we demonstrate that depending on the mode of colitis induction, IFNγ is critical for disease induction in the innate anti-CD40 mediated colitis model, whereas IFNγ production is dispensable in the CD4 T cell-dependent transfer colitis." (PMID 29416538, 2018). "While ILC3 promoted the pathogenesis of anti-CD40-induced innate colitis, targeted manipulation of ILC3 in the CD4 T cell transfer colitis model did not alter disease outcome." (PMID 29416538, 2018). "Intriguingly, in contrast to the anti-CD40 model of colitis, depletion of ILC in the Rag1−/− recipients of colitogenic CD4 T cells did not prevent induction of colonic inflammation." (PMID 29416538, 2018). "Thus, lack of ILC3 in Ahr-deficient mice may account for the resistance of anti-CD40 colitis." (PMID 29354125, 2017). "Since absence of colitis in DC-LMP1/CD40xRag−/− mice suggested an involvement of B and/or T cells in colitis development in DC-LMP1/CD40-mice, we next characterized T and B cells further." (PMID 28276457, 2017). "Overall, this data indicates that CD40-signalling in DCs was sufficient to induce fatal colitis, which depends on both, lymphocytes and the presence of high luminal loads of commensal bacteria." (PMID 28276457, 2017). "In summary, our results indicate that TL expression in IEC results in dampened intestinal inflammation in the anti‐CD40 model of colitis." (PMID 28474503, 2017). "We found that iCD8α cells play a pro‐inflammatory role in the development of disease in a colitis model induced by anti‐CD40 antibodies." (PMID 28474503, 2017). "To test if the development of colitis was dependent on T and B cells or commensal bacteria, we bred DC-LMP1/CD40-mice to T and B cell deficient Rag1−/− mice or treated DC-LMP1/CD40-mice with a mixture of antibiotics (ABX), respectively." (PMID 28276457, 2017). "We next sorted CD103+ and CD103− DCs from the mLNs of DC-LMP1/CD40-mice with colitis for expression analysis." (PMID 28276457, 2017). "The anti-CD40 model provided temporal synchronization, which is a feature unique to this model of colitis." (PMID 26780670, 2016). "Anti-CD40 induced colitis is dependent on a RORγt/IL-23 axis but key downstream cytokines are less well understood." (PMID 26780670, 2016). "As IL-17 and IL-22 are major downstream effectors of the IL-23 signalling axis we first investigated their role in anti-CD40 colitis." (PMID 26780670, 2016). "Since its description in 2006, the induction of colitis by injecting agonistic anti-CD40 antibody has become an important tool to assess ILC-driven acute colitis." (PMID 26780670, 2016).
colitis (continued). "We found that GM-CSF played a non-redundant role in both systemic and intestinal inflammation in the anti-CD40 model and was required for bacteria-induced innate colitis." (PMID 26780670, 2016). "By contrast with other models, anti-CD40 induced colitis follows discrete phases at well-defined time points following initiation, offering the opportunity to probe the role of leukocytes in the development and amplification of the inflammatory response." (PMID 26780670, 2016). "The results from these studies demonstrated that the CD40/CD40L interactions were an important element in the pathogenesis of colitis." (PMID 26528290, 2015). "The phenotypes of these DCs are the same as those of spleen-derived inflammatory E-cadherin + DCs that are present during anti-CD40-mediated colitis." (PMID 25651850, 2015). "Intraepithelial ILCs1 are increased in inflamed gut of CD patients and produce high amounts of IFN-γ in Rag1−/− mice treated with anti-CD40, a model of colitis characterized by wasting syndrome and severe intestinal inflammation." (PMID 25061260, 2014). "This is in line with previous work showing that both anti-CD90 (Thy-1) depletion in Rag1-deficient mice or use of Rag1.Rorc-double deficient mice, which principally lack IL-23R+ innate lymphoid cells, are similarly resistant to anti-CD40-induced colitis." (PMID 24586521, 2014). "On the other hand, as above specified, IL-17A and IFN-γ from NKp46-negative ILCs3 contribute to sustain inflammation in innate IBD models, such as anti-CD40 or H. hepaticus-induced colitis." (PMID 25061260, 2014). "In this model, injection of an agonistic CD40 mAb leads to focal colitis with a large accumulation of activated DCs in the MLN and colon." (PMID 20399121, 2010). "Antibodies blocking CD40 have been reported to dampen the severity of experimental colitis and a CD40 overexpression in Crohn's disease lesions has been known for a decade." (PMID 20634952, 2010). "To assess the role of T cell-derived signals in the accumulation of E-cadherin+ DCs, we utilized an anti-CD40 model of innate colitis." (PMID 20399121, 2010). "Additionally, anti‐CD40‐induced colitis mice showed significantly higher levels of mRNA expression of proinflammatory cytokines IL‐1β, IFNγ, and TNFα in colonic mucosa when compared to controls." (PMID 40410944, 2025). "Importantly, pharmacological inhibition of CD40 restored immune homeostasis and ameliorated colitis severity, underscoring the immunoregulatory potential of targeting this pathway." (PMID 41567217, 2025). "Moreover, animals with colitis demonstrated a significant variation in β diversity from the treatment (Anti-CD40/DSS + I3C) and control groups in their ileal samples." (PMID 39894796, 2025). "In the anti-CD40 induced colitis model, which is IL-23 dependent, ILC3s are a major source of GM-CSF, which is needed for these cells to move from cryptopatches to the intestinal tissue where they produce IL-22 and initiate an inflammatory immune cascade that results in intestinal inflammation." (PMID 41194916, 2025). "A similar phenomenon has been recently reported in the anti-CD40 colitis mouse model." (PMID 40471244, 2025). "However, in the anti‐CD40‐induced colitis mice treated with I3C, these functional profiles were largely reversed." (PMID 40410944, 2025). "We consistently observed similar findings in DSS- and anti-CD40-induced colitis models." (PMID 39894796, 2025). "In addition, in terms of β diversity, colonic samples from colitis mice were significantly different between control versus treatment (Anti‐CD40 + I3C) groups." (PMID 40410944, 2025). "However, ILC3 cells, which are absent in Rorc-/- x TRAG mice, are critical for the production of GMCSF driven eosinophilia and innate colitis in the anti-CD40 or H hepaticus infection of RAG-/-, which are also innate models of IBD." (PMID 38512959, 2024).
colitis (continued). "Therefore, we applied the anti-CD40 model to Rag2−/−x Ctla4−/− in comparison with Rag2−/− mice to see if there would be a difference in colitis severity." (PMID 39496592, 2024). "In mouse colitis, DCs within the colonic lamina propria express higher levels of costimulatory molecules (CD40, CD80, and CD86) and generate increased amounts of IL-12p40 and IL-23p19, which ultimately combine to form IL-23, thereby promoting Th17 differentiation." (PMID 37720208, 2023). "Recently, a novel selective RORγt (VPR-254) inhibitor was shown to reduce the production of key pro-inflammatory cytokines in an Anti-CD40 antibody-induced mouse model of colitis, implying that inhibition of RORγt can also suppress inflammation caused by innate immune-associated cytokines." (PMID 37122757, 2023). "Moreover, a constitutive expression of CD40 in dendritic cells resulted in the occurrence of fatal colitis in transgenic mice." (PMID 36558497, 2022). "As the absence of mTOR-mediated signaling reduced ILC3s’ capacity to secrete IFN-γ upon IL-23 stimulation, we next wished to probe whether RptorΔRORγt and/or RictorΔRORγt mice develop colitis following α-CD40 Ab treatment." (PMID 34341503, 2021). "Here, we identified Hh as a disease driver in the DC-LMP1/CD40 colitis model." (PMID 33550886, 2021). "The severe reduction of IFN-γ release together with a reduction of other cytokines (e.g. TNF, GM-CSF) upon colitis induction might explain why RptorΔRORγt and RictorΔRORγt mice were partially protected in an α-CD40-mediated colitis model." (PMID 34341503, 2021). "Lastly, we tested the impact of NFAM1 deletion on development of anti-CD40 induced colitis." (PMID 35095847, 2021). "Taken together, we identified the 60 kDa chaperonin GroEL from Hh as a potential antigen recognized by the immune system during early colitis onset, indicating that Hh could be a disease driver in the DC-LMP1/CD40 colitis model." (PMID 33550886, 2021). "We hypothesized that knocking out CD40 using our CRISPR/Cas9-based platform would prevent disease development in the CD40 agonist-induced colitis model." (PMID 32155151, 2020). "Additionally, neutralization of TL1A can attenuate α-CD40-induced colitis and DSS-induced chronic colitis in mice." (PMID 33193381, 2020). "For example, the data suggest animal to animal variability may be disease dependent, and the blood readouts have a higher variance in DSS vs anti-CD40 colitis." (PMID 32170183, 2020). "Using CD40 as a model target, we knocked out this key regulator through CRISPR/Cas9-based editing and validated the loss of CD40 gene function in the CD40 agonist-induced colitis model." (PMID 32155151, 2020). "The increased sensitivity of NIR readouts for colon permeability is shown using dextran sulfate sodium (DSS) and anti-CD40 murine colitis models in response to interleukin-22 immunoglobulin Fc (IL22Fc) fusion protein and anti-p40 monoclonal antibody treatments, respectively." (PMID 32170183, 2020). "Additionally, we would like to acknowledge Pharmacology leaders including Rajesh Kamath and others for their leadership in establishing the anti-CD40 colitis model in WT C57BL/6 mice." (PMID 32155151, 2020). "Interestingly, treatment with the CD40 peptide resulted in a reduction in MC-LR effects in the setting of pre-existing colitis that paralleled that which was seen in the CD40KO mice." (PMID 32498446, 2020). "In a mouse model of colitis induced by anti-CD40 antibodies, iCD8α cells secrete abundant granzymes to enhance intestinal inflammation, which may promote infiltration of molecules into the intestinal epithelium." (PMID 30804706, 2019). "Notably, reduced number of ILC3s in α-CD40-induced innate colitis in mouse models is compatible with the observation that fraction of ILC3s is reduced in inflamed intestine of CD patients compared with non-inflamed controls." (PMID 31358760, 2019). "Neutralization of TL1A by soluble DR3 ameliorates both DSS and anti-CD40 antibody-induced colitis." (PMID 31358760, 2019).
colitis (continued). "As colitis in DC-LMP1/CD40-mice is dependent on microbiota, also these differences might be relevant for disease onset." (PMID 30653608, 2019). "As especially DCs of the LP barrier tissue are in close contact with commensals and TLR-ligands, these differences might contribute to colitis as observed in the DC-LMP1/CD40-model." (PMID 30653608, 2019). "As IL-23R signals are central to upregulation of IL-1R by Th17 cells and IL-1R confers pro-survival signals for accumulation of T cells in the colon, the IL-23/IL-1 axis plays most likely an important role for the differences seen in the DC-LMP1/CD40-model for colitis." (PMID 30653608, 2019). "Furthermore, CD40-treated Gpr183−/−Rag1−/− mice developed only mild colitis with an inflammation score similar to that of PBS-treated Gpr183+/+Rag1−/− mice." (PMID 29343433, 2018). "Therefore, ILC appear to contribute uniquely to the innate immune response in the anti-CD40-mediated colitis model." (PMID 29948108, 2018). "The presence of IFNγ is a prerequisite in the anti-CD40 model of colitis whereas by using the T cell transfer model of colitis we clearly demonstrate that IFNγ is not necessary for the development of colitis as mice developed disease in the complete absence of IFNγ." (PMID 29416538, 2018). "Similarly, intraepithelial ILC1 have been demonstrated in patients with Crohn’s disease and have been suggested to contribute as a proinflammatory IFNγ-producing population to the pathology in an anti-CD40-induced colitis model in mice." (PMID 29526762, 2018). "Similarly, IFNγ-deficient mice were protected from DSS-induced colitis, and in the innate lymphoid cell (ILC) dependent anti-CD40-induced colitis." (PMID 29416538, 2018). "Continuous CD40-signalling disables CD103+ DCs to induce RORγt+Foxp3+ iTreg cells and causes accumulation of IL-17A+IFN-γ+ Th17/Th1 T cells, breakdown of tolerance to gut microbiota, dysbiosis and fatal colitis." (PMID 28276457, 2017). "By regulating the maintenance and function of ILC3, Ahr is critical for the clearance of Citrobacter rodentium, a murine pathogen that models human enterohemorrhagic Escherichia coli and enteropathogenic E. coli infections in the gut, as well as for the pathology of anti-CD40-incuced colitis." (PMID 29354125, 2017). "In fact, despite the relative increase of nTreg, they could not functionally ‘replace' iTregs to regulate T-cell-mediated inflammation and colitis in DC-LMP1/CD40-mice." (PMID 28276457, 2017). "Indeed, we found blocking GM-CSF prevented the accumulation of Ly6C+ inflammatory monocytes following anti-CD40 stimulation, in line with recent evidence for a key role for these cells in driving pathogenesis during anti-CD40 induced colitis." (PMID 26780670, 2016). "Despite data showing that migration of LTi ILC3s from the gut to the mesenteric lymph nodes is dependent on CCR7 expression, expression of CCR7 on ILCs was not assessed in that study and we were unable to identify CCR7 or CCR2 on intestinal ILC3s in anti-CD40 induced colitis." (PMID 26780670, 2016). "To determine whether ILC trafficking changed in colitis, we plotted the displacements of ILCs in steady-state and after anti-CD40 treatment." (PMID 26780670, 2016). "CD40 signaling has been shown to play an important role in inflammations such as colitis." (PMID 26809818, 2016). "Indeed, our data indicate a role for GM-CSF in the net egress of ILCs from cryptopatches in anti-CD40 induced colitis." (PMID 26780670, 2016). "Indeed, a study conducted in vivo showed the relevance of the CD40/CD40L system in the trinitrobenzene sulfonic acid (TNBS)-induced colitis." (PMID 26528290, 2015). "Although CD40 signalling is critical for the differentiation of inflammatory monocytes into E-cadherin + inflammatory DCs and the promotion of anti-CD40-mediated colitis has been confirmed in Rag1 KO mice, little is known regarding the role of E-cadherin + inflammatory DCs in tumour immunity." (PMID 25651850, 2015).